AGXT (alanine--glyoxylate aminotransferase)
Diseases named in the same sentence as AGXT in open-access papers (continued):
Sharing a sentence is not in itself a finding about the gene and the disease.
kidney disease (2 papers, 2012 to 2024). "The crystal structure of the peroxisome enzyme alanine-glyoxylate aminotransferase bound to its targeting receptor Pex5p explains why even minor fold defects prevent targeting of the enzyme and cause kidney disease." (PMID 22529745, 2012).
AGXT also shares sentences with these, for which no sentence is quoted: metabolic disease (6 papers); hereditary sensory and autonomic neuropathy type 1 (3); nephrocalcinosis (3); renal failure (3); chronic kidney disease (2); genetic disorder (2); liver disease (2); autonomic neuropathies (1); axonal neuropathy (1); breast carcinoma (1); ciliopathy (1); colorectal cancer (1); deficiencies (1); dementia (1); Dent disease (1); diabetes (1); distal renal tubular acidosis (1); end-stage renal disease (1); gastric cancer (1); Hepatic fibrosis (1); Kabuki syndrome (1); kidney cancer (1); left ventricular hypertrophy (1); liver cirrhosis (1); lung carcinoma (1); metastatic colorectal cancer (1); myoclonus epilepsy (1); Nephropathy (1); non-alcoholic steatohepatitis (1); pancreatic cancer (1).
A further 4 diseases each share a sentence with AGXT in 1 paper.